BUD13 (BUD13 spliceosome associated protein)
Description:
Involved in pre-mRNA splicing as component of the activated spliceosome. As a component of the minor spliceosome, involved in the splicing of U12-type introns in pre-mRNAs.
Synonyms: MGC13125; fSAP71; Cwc26; ACHPS
Tractability: Small molecule: a structure with a bound ligand is known. PROTAC: UniProt records ubiquitination sites on it; ubiquitination databases record sites on it; its protein half-life has been measured.
Gene: Protein-coding gene on chromosome 11 (116,748,170 to 116,773,039, reverse strand). Ensembl gene ENSG00000137656.
Subcellular location: Nucleus
Subcellular location (Human Protein Atlas): Nucleoplasm
Pathways (Reactome):
Metabolism of RNA: mRNA Splicing - Major Pathway
Gene Ontology:
Molecular function: protein binding; RNA binding
Biological process: mRNA splicing, via spliceosome; U2-type prespliceosome assembly
Cellular component: nucleoplasm; nucleus; spliceosomal complex; U12-type catalytic step 2 spliceosome; U2-type catalytic step 1 spliceosome; U2-type precatalytic spliceosome; RES complex; U2 snRNP; U2-type spliceosomal complex
Genetic constraint (gnomAD): Loss-of-function variants: 44 observed, 62.24 expected, observed/expected ratio (o/e) 0.71, 90% interval 0.55 to 0.91. The upper end of that interval is the gene's LOEUF score, 0.91, which puts it in group 3 of 6, group 1 being the genes least tolerant of losing a copy. Missense variants: 818 observed, 808.19 expected, observed/expected ratio (o/e) 1.01, 90% interval 0.95 to 1.07. Synonymous variants: 293 observed, 287.96 expected, observed/expected ratio (o/e) 1.02, 90% interval 0.92 to 1.12.
Homologues: Orthologues: chimpanzee BUD13 (99% identical), macaque BUD13 (95% identical), pig BUD13 (82% identical), dog BUD13 (81% identical), rabbit BUD13 (79% identical), guinea pig BUD13 (78% identical), mouse Bud13 (77% identical), rat Bud13 (77% identical), tropical clawed frog bud13 (53% identical), zebrafish bud13 (41% identical), Drosophila melanogaster CG13625 (31% identical), Caenorhabditis elegans bud-13 (25% identical).
Diseases named in the same sentence as BUD13 in open-access papers:
BUD13 is named in the same sentence as 27 diseases in open-access papers, as found by Europe PMC text mining. Sharing a sentence is not in itself a finding about the gene and the disease. The quoted sentences say what the papers report.
metabolic syndrome (14 papers, 2014 to 2025). A cluster of metabolic risk factors for CARDIOVASCULAR DISEASES and TYPE 2 DIABETES MELLITUS. "The SNP in BUD13, a main SNP in our study, was similarly highly associated with metabolic syndrome and hyperlipidemia in Asian countries, such as China and Taiwan." (PMID 36171780, 2022). "BUD13 polymorphisms have been associated with elevated serum lipid levels and metabolic syndromes (PMID: 24989072, PMID: 28659142)." (PMID 34354115, 2021). "The interaction analysis suggests rs10488699-rs2187126 pair of the BUD13 gene to confer significant risk (Interaction odds ratio = 14.38, P = 7.17 × 105) towards dyslipidemia by elevating the TC levels (β = 37.13, p = 6.614 × 105)." (PMID 28610615, 2017). "Of these variants, rs17440396, rs10488699 and rs2187126 are associated with increased risk towards dyslipidemia and belong to BUD13 regulatory gene, while rs6589566 is risk reducing and belongs to ZPR1 regulatory gene." (PMID 28610615, 2017). "In a recent meta-analysis, comprising 13 independent European ancestry studies, the SNPs of ZNF259 rs2075290 and BUD13 rs10790162 were identified as the top association SNPs for metabolic syndrome." (PMID 24780069, 2014). "Additionally, the risk of developing a metabolic syndrome was associated with BUD13 through case-control studies." (PMID 35053791, 2021). "Variants in well-known triglyceride-related genes such as BUD13 and SIK3 are known to be associated with triglyceride levels, lipid traits, overall lipid homeostasis, or metabolic syndrome." (PMID 33763119, 2021). "In the present study, we observed variants that belong to BUD13, ZPR1 genes and APOA5-APOA4 intergenic region as commonly associated with TC/LDLC and in turn with dyslipidemia." (PMID 28610615, 2017). "While more and more studies demonstrated that BUD13 played a potential role in the pathogenesis of metabolic syndrome (MetS)." (PMID 28659142, 2017). "Exome-wide association studies (EWASs) identified eight SNPs related to the dyslipidemia-dominant subtype with genome-wide significance, which were located in the genes APOA5, BUD13, ZNF259, and WNT4." (PMID 36551856, 2022). "For instance, ZPR1 and BUD13 were well-documented for lipid level, HERPUD1 was found related to HDL-C in the Korean population, and the APOA5 and CETP also showed evidence of contributing to triglycerides, metabolic syndrome, and HDL-C." (PMID 35238325, 2022).
coronary artery disease (5 papers, 2010 to 2020). "Either individually or in interaction with other SNPs of 11q23.3 region, the variants of BUD13 gene are reported to elevate lipid traits as well as conferring risk towards coronary disease." (PMID 33298998, 2020). "BUD13 and ZPR1 were found to be associated across anatomical categories of coronary artery disease in an Indian study (Pranavchand, Kumar & Reddy, 2017)." (PMID 30631647, 2019). "This region of the ZNF259/BUD13, APOA1/C3/A4/A5 genes has also been associated with coronary artery disease." (PMID 25688259, 2015).
hypertriglyceridemia (5 papers, 2014 to 2022). A laboratory test result indicating elevated triglyceride concentration in the blood. "We found several novel variants associated with different lipemic traits: rs3825041 in BUD13 with hypertriglyceridemia, rs7252453 in CILP2 with decreased risk to hypercholesterolemia and rs11076176 in CETP with increased risk to low high density lipoprotein cholesterol." (PMID 35669185, 2022). "Our objectives were to determine the association of the BUD13/ZNF259 SNPs and their haplotypes with hypercholesterolaemia (HCH)/hypertriglyceridaemia (HTG) and to identify the possible gene–gene interactions among these SNPs." (PMID 24780069, 2014).
breast carcinoma (2 papers, 2019 to 2025). "We found that four interacting proteins of SNRPG are also upregulated in Cluster 1 of basal breast cancer patients with respect to Cluster 2: BUD13, CWC15, and SNRNP70 and ZMAT12, forming a cluster of interacting proteins enriched for the U2-type spliceosomal complex." (PMID 40867231, 2025). "While there is no known association between APOA4 and breast cancer risk, two plausible candidates (ZNF259 and BUD13) map approximately 42 kb and 57 kb centromeric to the 11q23.3 breakpoint." (PMID 30496607, 2019).
glioblastoma (2 papers, 2022 to 2024). The most malignant astrocytic tumor (WHO grade IV). "Research on glioblastoma (GBM) has revealed that METTL3 enhances the stability of BUD13 mRNA through m6A methylation." (PMID 39295872, 2024).
Obesity (2 papers, 2021 to 2024). Accumulation of substantial excess body fat. "In summary, the obtained results suggest that regions 8q22-24, 11q23-25, and 12q13-15 are very likely to contain genes like VPS13B, APOA5, ZPR1, BUD13, and FAIM2 that control obesity-related factors in Iranian families with MetS21,22,27,28,31,32." (PMID 33727680, 2021).
prostate carcinoma (2 papers, 2021 to 2022). A carcinoma that arises from epithelial cells of the prostate gland. "In prostate cancer, circSERPINA3 competed with miR-653-5p for binding BUD13, and regulated apoptosis, autophagy, and aerobic glycolysis." (PMID 36463205, 2022).
Achalasia (1 paper, 2025). A disorder of esophageal motility characterized by the inability of the lower esophageal sphincter to relax during swallowing and by inadequate or lacking peristalsis in the lower half of the body of the esophagus. "Five individuals identified with nucleotide substitutions in BUD13 reported lipodystrophy with dysmorphic facial features, microcephaly, achalasia, intellectual disability, and progressive hearing loss." (PMID 41191133, 2025).
atherosclerosis (1 paper, 2020). A disease characterized by the build-up of fatty material and calcium deposition in the arterial wall resulting in partial or complete occlusion of the arterial lumen. "Since the SNPs at 11q23.3 region harbouring apolipoprotein coding genes namely APOA1, APOC3, APOA4, APOA5 and regulatory genes BUD13, ZPR1, SIK3 were found to be associated with defective lipid metabolism, this region was thought to play an important role in atherosclerosis and CAD risk." (PMID 33298998, 2020).
developmental delay (1 paper, 2025). "Biallelic variants in BUD13, a spliceosome associated protein, have been linked to syndromic developmental delay and hearing loss, emphasizing the pathogenic potential of spliceosome dysfunction." (PMID 41191133, 2025).
diffuse large B-cell lymphoma (1 paper, 2022). "Previous research found DBH-AS1 recruited BUD13 enhancing FN1 stability, and promoted cell proliferation, migration, and invasion in diffuse large B-cell lymphoma." (PMID 36463205, 2022).
glioma (1 paper, 2025). A benign or malignant brain and spinal cord tumor that arises from glial cells (astrocytes, oligodendrocytes, ependymal cells). "It stabilizes the mRNAs of BUD13 and CDK12, thereby promoting MBNL1 phosphorylation and subsequently facilitating the formation of glioma vasculogenic mimicry (VM)." (PMID 40469294, 2025). "The specific mechanism involves METTL3 stabilizing the mRNAs of BUD13 and CDK12, leading to their overexpression, which in turn promotes the phosphorylation of MBNL1 and facilitates the VM process in gliomas." (PMID 40469294, 2025).
ischemic stroke (1 paper, 2023). A stroke disorder caused by obstruction of blood flow to the brain, due to thrombotic (local blood clot formation) or embolic (due to a blood clot or other material traveling from another site) event. "BUD13, a subunit of the retention and splicing complex, may significantly increase the risk of ischemic stroke by affecting APOA1 leading to elevated TG and VLDL45,46." (PMID 36720935, 2023).
tumor (2 papers, 2021 to 2022). "Since we learned from previous literature that BUD13 could exert its function in tumor through regulating mRNA stability, we wanted to explore whether BUD13 could regulate the mRNA stability of SERPINA3." (PMID 34861864, 2021). "To confirm the roles of BUD13, CDK12, and MBNL1 in tumor growth in vivo, we subcutaneously injected GBM BUD13(-) cells, CDK12(-) cells, MBNL1(+) cells, or a combination of the three cells to construct nude mice xenograft models." (PMID 36463205, 2022).
genetic disorders (1 paper, 2021). "Although no rare variants in BUD13 are reportedly causative in other genetic disorders, a copy number variant (CNV) investigation revealed a deletion in chromosome 11 spanning BUD13 in an individual with an NDD phenotype." (PMID 35053791, 2021).
BUD13 also shares sentences with these, for which no sentence is quoted: hypercholesterolaemia (3 papers); cardiovascular disease (2); hyperlipidaemia (2); fatty liver (1); hearing loss (1); hypercholesterolemia (1); influenza (1); Intellectual disability (1); lipodystrophy (1); microcephaly (1); respiratory diseases (1); specific language impairment (1).